FOXP3 (forkhead box P3)
Diseases named in the same sentence as FOXP3 in open-access papers (continued):
Sharing a sentence is not in itself a finding about the gene and the disease.
tumor (continued). "The FOXP3+ Tregs are known for their immunosuppressive functions and their presence in the TME may suppress the anti-tumor immune response by the inhibition of the activity of cytotoxic T cells and other effector immune cells, contributing to immune evasion by the cancer cells." (PMID 38674427, 2024). "Moreover, BG/OVA@EcN exhibited the strongest ability to promote tumor infiltration of the activated IFN‐γ+CD8+ T and CD69+CD8+ T cells, as well as the activated CD69+CD4+ T cells, while decreasing the numbers of Tregs (Foxp3+CD25+CD4+CD3+CD45+ cells)." (PMID 38009498, 2024). "In addition, an analysis of the tumor microenvironment revealed a simultaneous reduction in CD3+CD8+ T-cell infiltration and inflation in the tumor-resident activity of CD4+FOXP3+ T-reg cells in SNORA38B OE conditions, while the exact opposite effect was observed in SNORA38B KO samples." (PMID 38474168, 2024). "Studies have also shown that FOXP3-positive regulatory T cells in the tumor microenvironment secrete immunosuppressive cytokines such as IL-10 and TGF-β, inhibiting cytotoxic T cells and enabling tumor cells to evade immune surveillance in various cancer types." (PMID 40741180, 2024). "Thus, FOXP3-positive Treg cells in CHL represent the “tip of the iceberg” of the population of regulatory cells that contribute to immunosuppression in CHL and make this tumor different from others." (PMID 39200145, 2024). "Lactate, produced abundantly by tumor cells, exerts profound immunosuppressive effects by impeding the proliferation of effector T cells and NK cells, inhibiting IFN-γ production in CTLs, and promoting Treg survival in a Foxp3-dependent manner within a lactate-rich, glucose-depleted TME." (PMID 38785789, 2024). "FoxP3 is a key regulatory gene for the development of Tregs that inhibits the antitumor immune response by producing immunosuppressive molecules, such as IL-10, CTLA-4 and PD-1, and releasing vascular endothelial growth factor (VEGF) to stimulate tumor angiogenesis." (PMID 39534095, 2024). "Hayashi reported that Foxp3+ T cell expression might play a role in nodal metastasis and exhibited a significant correlation with the weak immune response, onset of OSCC, and enhancement of tumor malignancy." (PMID 39744628, 2024). "Forkhead Box P3 (FOXP3) CD4 + regulatory T cells are a subset of type 2 CD4 + T-helper cells (Th2) that suppress CTL activity, boost B-lymphocyte proliferation and may instigate an anti-inflammatory, immune response that encourages tumor progression." (PMID 38326735, 2024). "In addition, there was no alteration in the proportion of CD25+ FoxP3+ Treg cells in the tumor site." (PMID 37333490, 2023). "There was also intratumoral heterogeneity of these mechanisms, for example, the virtual absence of Granzyme B + iTILs in the tumor center when compared to other compartments or the presence of FOXP3 + TILs at the invasive margin but not in other tumor regions (patient 7)." (PMID 36562826, 2023). "The relationship between a high number of Foxp3+ lymphocytes and a shorter overall survival highlights the fact that the amount of Foxp3+ cells should be considered to be an important negative prognostic marker in these neoplasms." (PMID 36766393, 2023). "Moreover, mIHC staining confirmed different expression levels of CD68+ &APOE+ macrophages, FOXP3+ &TNFRSF4+ Tregs, VEGFA, and TGFβ signaling between the tumor microenvironment of the de novo mild OLK and the OLK with moderate to severe dysplasia in clinical study." (PMID 36914617, 2023). "Studies have shown that a higher number of FOXP3-positive Tregs identifies patients with BC with no recurrence and shorter OS, suggesting that Tregs may impede anti-tumor immune responses." (PMID 37767092, 2023).
tumor (continued). "Our experiments mimicking the condition of tumor initiation when only a low number of breast CSCs are present in comparison to the infiltrating effector CD4+T cells, revealed that CSCs convert CD4+CD25− T cells into immunosuppressive CD4+CD25+FOXP3+ Treg cells in a contact-independent manner." (PMID 38038865, 2023). "In addition to FOXP3+ Tregs, marginal tumor regions have more subpopulations with an immunosuppressive phenotype, including CD163+ macrophages, CD11b+ neutrophils, and CD274 (PD-L1)+ tumor cells." (PMID 37529035, 2023). "In addition, the ligation of PD-L1 on tumor cells to PD-1 on lymphocytes induces the apoptosis of tumor-specific T cells and promotes the differentiation of CD4+ T cells into forkhead family transcription factor 3 (Foxp3)+ Tregs." (PMID 37266424, 2023). "Furthermore, no changes in the CD8/FoxP3 ratio were observed in untreated index tumor at 3d or 7d after ablation." (PMID 37883367, 2023). "Importantly, analysis of the relative proportion of Tregs (CD3+FOXP3+) within the entire population of infiltrating T cells (CD3+) revealed that Tregs were significantly enriched in the WT and shC tumours relative to the TAZ‐KO and shTAZ tumours, respectively." (PMID 37716913, 2023). "Notably, the majority of CD4+ TILs in MC38 tumours did not express FoxP3 or T-bet (40-75%), suggesting that MC38 tumours are heavily infiltrated by effector subsets other than TH1 and TREG cells, likely TH2 or TH17 cells." (PMID 37153625, 2023). "In addition, we have shown that P60 exerts direct antitumor effects, inhibiting tumor growth not only in immune competent mice but also in animals lacking a functional immune system, suggesting that Foxp3 exerts intrinsic effects in BRCA cells." (PMID 37766222, 2023). "Additionally, higher infiltration levels of FOXP3+ Treg lymphocytes and CD163+ M2-like macrophages were found in the tumor microenvironment of RS compared to that of CLL, suggesting an enhanced immune suppression and resistance against adaptive immunity that promote tumor growth and progression." (PMID 36831361, 2023). "We identified tumor cells with FOXP3expression, but could not verify any difference in tumor cell FOXP3 expressionbetween treatments." (PMID 36880147, 2023). "Next, we compared the proportion of CD4, CD8, CD19, CD68 and Foxp3 positive cells in lymphocytes of patients with high and low expression of ICOSLGTCs, as well as the proportion of CD4, CD8 positive cells and Fopx3+ cells, and divided them into invasive Frontier and tumor center for analysis." (PMID 37842091, 2023). "Clustering IL10, TGFβ1 and FOXP3 may also provide a better understanding of the contribution of the regulatory subsets to the systemic immunodeficiency and lack of tumour clearance observed in CLL patients." (PMID 36973425, 2023). "To complement the multiplex IHC experiments showing enrichment of CD4+/FOXP3+ and CD8+/PD-1 T cells in HCC samples of patients affected by HIV, we performed an exploratory targeted transcriptomic analysis of a smaller subset of 48 patient samples with viable tumour tissue." (PMID 37274775, 2023). "Furthermore, sorafenib treatment increases the number of CD4 + CD25 + FOXP3+ Treg infiltrating HCC and inhibits CXCR4, preventing drug resistance due to the immunosuppressive microenvironment established following sorafenib treatment, suppressing tumor growth." (PMID 36769116, 2023). "Tumor draining lymph nodes (TdLN) and tumor-infiltrating lymphocytes (TILs) were harvested from tumor-bearing mice (or inguinal lymph nodes from control naive animals) at day 20 post-tumor injection, and the expression of CD45, CD4, Foxp3, CD49b, and IL-10 was analyzed by flow cytometry." (PMID 35860556, 2022).
tumor (continued). "Thus, density numbers of infiltrating CD8+, CD4+, and FOXP3+ T-cell lymphocytes, CD20+ T-cell lymphocytes, and CD68+ and CD163+ macrophages were separately evaluated in both the tumor nests and surrounding stroma, and the mean numbers were correlated with the mean values for NLR, PLR, SII and LMR." (PMID 35958590, 2022). "However, type 2 CD4+ T-helper cells (Th2), including Forkhead box P3 (FOXP3) CD4+ regulatory T-cells, inhibit CD8+ cytotoxic T-cell function, promoting an anti-inflammatory immune response that could stimulate tumor growth." (PMID 36010863, 2022). "However, the number of Tregs (CD4+ CD25+ FoxP3+) were significantly lower in the tumors of LECMHC-II−/− mice but not different in tumor-draining LNs or spleens." (PMID 36362253, 2022). "Interestingly, during tumour development, CD4+T cells may progressively transdifferentiate into IL-17A+ FOXP3+ and ex-Th17 IL-17A- FOXP3+ T cells." (PMID 36569832, 2022). "Additionally, some of the ICIs have been shown to deplete tumor Treg cell populations, either by inducing antibody-dependent cell-mediated cytotoxicity (ADCC) or by downregulating forkhead box P3 (FOXP3), a protein that functions as a master regulator in the development and function of Tregs." (PMID 35141049, 2022). "Therefore, associations between TIM-3 expression and improved DFS in CD8+ and FoxP3-expressing CD8+ TILs provide evidence for its immunomodulatory roles, which may be beneficial in limiting tumor progression." (PMID 35804964, 2022). "TIL Foxp3 (+) levels predicted independent of age, gender, TNM stage, and HPV infection as well as level of stromal desmoplasia, tumor invasion, and nuclear polymorphism, but more pronounced among tumor HPV (+) than HPV (−) patients." (PMID 35326661, 2022). "In fact, TIM-3 is widely expressed on T antigenic tumor-specific lymphocytes, in peripheral blood and in tumor-infiltrating lymphocytes (TIL), both CD4+ and CD8+, and overexpressed on so-called exhausted T cells (especially CD8+ and CD4+ Treg Foxp3+) in tumor settings." (PMID 35207500, 2022). "One possible rationale for the observed results could be a suppressive function of FoxP3+ TILs in “immune-desert” tumours and a lack of function in “inflamed” tumours." (PMID 35140715, 2022). "In addition, patients with longer survival had higher frequencies of tumor-infiltrating non-proliferating (Ki-67−) conventional and regulatory (Foxp3+) CD4 T cells and lower frequencies of infiltrating proliferating (Ki-67+) CD4 T cells." (PMID 35662283, 2022). "As FoxP3+ Treg cells are known to suppress anti-tumor immunity in NSCLC, these findings suggested that IL-9 derived from Treg cells and TIL might control immune responses and tumor growth." (PMID 35514957, 2022). "As both 5-FU and cisplatin chemo-immunotherapies increased activated and proliferating CD8+ and CD4+Foxp3- T cells, we depleted CD8+ or CD4+ T cells throughout the treatment schedule in AB1-HA tumor-bearing mice to test whether these cells were required for effective chemo‐immunotherapy." (PMID 35634282, 2022). "The profile of tumor infiltrating immune cells was analyzed by FACS and the results revealed that the percentage of immunosuppressive CTLA4+ or PD-1+ on CD8+ T cells and CD4+CD25+Foxp3+ Tregs was significantly reduced in nCHI3L1 Ab treatment group compared to that in the IgG group." (PMID 34987649, 2022). "A growing number of studies have shown that FOXP3-positive regulatory T (Treg) cells in TME secrete immunosuppressive cytokines, including IL-10 and TGF-β, and inhibit CD8-positive cytotoxic T cells, allowing tumor cells to escape the host’s immune surveillance in several cancers." (PMID 35159384, 2022). "In summary, we revealed that miR‐192‐5p promotes GC EMT, thereby promoting malignancy and FOXP3+ Treg cell differentiation via RB1/NF‐κBp65/IL‐10 axis, thereby highlighting the miR‐192‐5p/RB1/NF‐κBp65/IL‐10 pathway as a new therapeutic strategy for tumour immunotherapy in GC." (PMID 35969010, 2022).
tumor (continued). "Specifically, predominant type I tissues had higher regulatory (Foxp3+) T-cell infiltration in the tumor area (0.73% [0.86%] vs 0.20% [0.19%]; P = .04), nontumor area (1.48% [1.48%] vs 0.37% [0.29%]; P = .03), and total area (0.89% [0.88%] vs 0.24% [0.19%]; P = .03)." (PMID 36239936, 2022). "We compared the immune repertoire between treatment groups by assessing CD8+ T cells, CD4 + FOXP3+ Tregs, the CD8+ T cell to Treg ratio, CD45 + CD11b + CD103+ dendritic cells, and CD44highCD62Llow effector memory CD8+ and CD4+ T cells in spleen samples from 4T1-luc tumor-bearing mice." (PMID 35681672, 2022). "The expression of multiple immune cells (CD8, Foxp3, CD68, CD163, CD20, CD11c, CD66b, CD56, PD-L1, INF-γ, Ki67 and VEGFR-2) in the tumor center (TC), tumor invasive front (< 150 μm from the tumor center, TF) and peritumoral region (≥ 150 μm from the tumor center, PT) was evaluated via comparison." (PMID 36195882, 2022). "Infiltration of type 2 (CD4+ T-helper cells or Th2), including Forkhead box P3 (FOXP3) CD4+ regulatory T-cells, inhibits cytotoxic T-cells (CTL) function, supports proliferation and promotes an adaptive anti-inflammatory immune response that is responsible for tumor growth." (PMID 36003772, 2022). "Manual gating validated that PD-1+GB−CD8+ exhausted T cells, Foxp3+CD152+CD4+ Treg, and PD-1+CD45RO+CD4+ memory T cells were enriched; while GB+CD56+ active NK cells and PD-1−GB+CD8+ activated T cells were depleted, specifically in S2 tumours compared to S1 or S3 tumours or both." (PMID 35301339, 2022). "Therefore, and since we observed no significant increase of Tgfb1 mRNA expression or of FoxP3+CD4+ Tregs in βΑ tumors, we wondered whether Activin-A stimulates tumor growth by promoting IL4 signaling." (PMID 35580932, 2022). "FoxP3+ T cells could be without prognostic relevance since lack of T cell migration into the tumour was assumed to be the main immune tolerance promoting factor in this phenotype." (PMID 35140715, 2022). "Furthermore, a strong positive correlation was observed between frequencies of FoxP3+Helios+ T cells and CD4+PD-1+ T cells in NILs in CRC patients, and it was found to be stronger in early tumor stages compared to advanced stages (r = 0.818, p = 0.005 [early]; r = 0.393, p = 0.206 [advanced])." (PMID 36146549, 2022). "However, in all tumor types GITR expression was highest on CD4+ and CD4+ FoxP3+ TIL." (PMID 36155259, 2022). "Upon combination treatment, we anticipate an increase of CD3+, CD8+ and FoxP3 + T cells in the TME, a dynamic change of the immune cell populations in the peripheral blood and an increased tumor regression as compared to historical controls due to the increased immune infiltrate within the tumor." (PMID 35840912, 2022). "Because the tumor microenvironment influences the TIL response, it will be important to further characterize the TILs for both antitumor and suppressive phenotypes and quantitate the ratios of activated CTLs (CD8+ICOS++) versus TRegs (CD4+FOXP3+) posttreatment." (PMID 35094188, 2022). "One study observed Foxp3+ T cells directly infiltrating into the tumor, while another study could not support these results." (PMID 35392957, 2022). "As MSCs, tumor cells have the ability to promote the generation of Treg cells (CD4+CD25+Foxp3+) through mechanisms that may or may not involve cellular contact between T lymphocytes and tumor cells or MSCs." (PMID 36661506, 2022). "We found that tumours with G-CSFhigh and CAIX+ phenotypes independently displayed highly significant positive correlations with the presence of intratumoural lymphocytes expressing CD8, PD-1, FOXP3, TIM3, and LAG3, with carcinoma cells expressing PD-L1, and with CD163+ M2 macrophages." (PMID 33804486, 2021). "However, we suggest that the immunosuppressive capacity of the regulatory population of FoxP3-expressing lymphocytes may be important in CRC to control continuous and aggressive inflammatory responses that may favor tumor proliferation." (PMID 34440038, 2021).
tumor (continued). "Finally, compared to FoxP3, GARP is expressed by a greater diversity of cells contributing to the immunosuppressive environment including tumor cells themselves and platelets that are now recognized to play a major role in tumor progression via the production of biologically active TGF-β." (PMID 34571713, 2021). "Our current finding revealed that DPP-4i enhanced tumor-infiltrating MPO+, CD4+, F4/80+, Foxp3+ cells, and MDSCs, but decreased CD8+ T lymphocytes in metastatic sites, indicating that DPP-4i may induce tumor-immunosuppressive microenvironment by enhancing tumor-infiltrating immune-suppressive cells." (PMID 34631556, 2021). "The heterogeneous association of FOXP3 with prognosis in SCLC may be partly attributable to non-uniform cut-off values, tumor stage, and detection locations (primary vs metastatic)." (PMID 34362829, 2021). "CD4+Foxp3+CD25+ Tregs are exclusively enriched in the TME through their recruitment by cytokines/chemokines and certain growth factors, namely vascular endothelial growth factor and transforming growth factor-β, exerting an anti-tumour immune response and tumour evasion." (PMID 34062862, 2021). "Foxp3+ Tregs are the major constituent of the TILs in claudin-low TNBC tumors and it has been speculated that the recruitment of Foxp3+ Tregs to the TME inhibits an effective anti-tumor immune response of checkpoint inhibitors." (PMID 34283088, 2021). "However, there were no significant reductions in the frequency of FoxP3+ Tregs in the tumour, blood, or spleen." (PMID 33964937, 2021). "CCR4 is expressed predominantly by effector Tregs, which are the most abundant cell type among FOXP3+ T cells in tumor tissue; in addition, CCR4 ligands produced by cancer cells or by infiltrating macrophages appear to be involved in migration and infiltration of Tregs into various tumor tissues." (PMID 34445615, 2021). "In tumor tissues examined 14 days after the last immunization, no FOXP3+ T cells were identified in the mice treated with the combination therapy, whereas scarce FOXP3+ T cells were found in the corresponding tumors from mice treated with the IFN-DC vaccine alone." (PMID 35008305, 2021). "The TGFβ1 level (lower or higher than the median) in tumor stroma was positively associated with that of PD-L1 in tumor stroma and tumor (P ≤ 0.001, R = 0.428, 0.388), and CTLA4 in tumor stroma (P ≤ 0.001, R = 0.350), but not CD8 or FoxP3 in tumor stroma (P = 0.970; 0.249, respectively)." (PMID 34095135, 2021). "Moreover, considering the elevated FOXP3, IL-6, and IL-17 levels in these cells, CML cell-derived exosomes may induce T cell fate toward tumor favorable T cells instead of conventional activated T cells (Th1, Th2, CTL, etc.)." (PMID 34493241, 2021). "Given the heterogeneous patterns of change in TIL subpopulations and the fact that the balance of immune-reactive versus immune-tolerant cells may be more relevant to deciphering the tumor immune contexture, the ratios of CD8+/FOXP3+, CD4+/FOXP3+, and CD3+/FOXP3+ in individual tumors were derived." (PMID 32852603, 2021). "The mechanisms in which Foxp3+ T cells promoted HCC progression might include fostering angiogenesis, decreasing CD8+ T cells, progressively reducing CD4+ CTLs, and boosting the formation of portal vein tumor thrombi (PVTT) and so on." (PMID 34566989, 2021). "In conclusion, we identified a new candidate oncogenic lncRNA WFDC21P that promotes tumor progression through WFDC21P/Ran/Akt/GSK3β/β-catenin axis and that is positively regulated by transcription factor FOXP3 in GC, which may provide a novel biomarker and therapeutic target for GC." (PMID 34601496, 2021). "Also, long-term exercise increased CD8+ or CD3+ infiltration or activation, which contributed to tumor suppression, while it increased the CD8+/FoxP3+ ratio in tumors and might diminish FoxP3+ tumor infiltration, leading to tumor suppression." (PMID 33808154, 2021).